CD163 (CD163 molecule)
Diseases named in the same sentence as CD163 in open-access papers (continued):
Sharing a sentence is not in itself a finding about the gene and the disease.
prostate carcinoma (29 papers, 2017 to 2026). A carcinoma that arises from epithelial cells of the prostate gland. "The risk of death from prostate cancer in the same cohort was almost twofold higher in patients with high amount of CD163+ TAMs versus those with lower numbers." (PMID 33194645, 2020). "IHC analysis of tissue specimens derived from 93 Italian prostate cancer patients has identified that high amount of CD163+ TAMs was associated with extracapsular extension (Gleason score > 7) and worse biochemical recurrence-free survival rates." (PMID 33194645, 2020). "In addition, immunosuppressive cells such as FOXP3-positive regulatory T cells and CD163-positive tumor-associated (M2) macrophages were also found to be enriched in prostate cancer and associated with a more unfavorable patient outcome." (PMID 31549213, 2019). "Men with abundant CD163+ M2 macrophages in prostate tissue have a higher risk of lethal prostate cancer and the interpretation is that the presence of these suppressor cells, CD163+ M2 macrophages, and CD4+ FoxP3+ Tregs may promote an immunosuppressive microenvironment." (PMID 35326519, 2022). "In a prostate cancer model, transcriptomic analysis of the tumor microenvironment revealed an increase in the expression of genes associated with pro-tumorigenic macrophages, such as Arg1 Cd163, Mrc1, Retnla, Lyve1, in aged (20–24 months) compared to young male C57BL/6J mice." (PMID 33441138, 2021). "To investigate the potential correlation between EAF2 expression and macrophage recruitment in prostate cancer patients, we conducted immunohistochemistry (IHC) staining against CD163." (PMID 38969982, 2024). "Our study demonstrated that in specimens of human prostate cancer, the expression of EAF2 was notably downregulated, and this decrease was inversely associated with the number of CD163-positive macrophages that infiltrated the cancerous tissue." (PMID 38969982, 2024). "Our findings suggested that EAF2 was involved in the infiltration of CD163-positive macrophages in prostate cancer via MIF." (PMID 38969982, 2024). "Considering only the presence of macrophages in the enrolled prostate cancer lesions, a significant increase in M2 macrophages (CD163-positive cells) was observed in PCM+ as compared to PCM− (PCM− 102.7 ± 13.7; PCM+ 163.3 ± 21.2; p = 0.008)." (PMID 39457506, 2024). "To further support our findings, we analyzed CD68 and CD163 mRNA expression in the TCGA prostate cancer dataset (TCGA-PRAD), which contains 495 PCa samples." (PMID 38189834, 2024). "In prostate cancer, elevated PD-L1 expression was significantly correlated with CD163+ TAM invasion and Gleason score; furthermore, patients with high levels of CD163+ TAM and PD-L1 expression had shorter biochemical recurrence-free survival." (PMID 39199574, 2024). "Evaluation of TAMs in prostate cancer (PCa) patients identified the immunosuppressive TAM marker CD163 in adjacent normal epithelium as an independent predictor of metastases or PCa death." (PMID 35075795, 2022). "CD163+ M2 macrophages correlate with worse prostate cancer clinicopathologic characteristics and outcomes." (PMID 36229464, 2022). "In a second cohort of patients with Gleason grade group ≥ 3 prostate cancer, global macrophage expression of CD163 was unchanged with enzalutamide treatment." (PMID 34588590, 2021). "Increased CD68+ and CD163+ macrophage infiltration was found in a cohort of 60 Chinese prostate cancer patients receiving preoperative Bicalutamide-based ADT." (PMID 33194645, 2020). "In fact, Liu and colleagues demonstrated that high levels of TRIB1 in prostate cancer correlate with CD163+ macrophage infiltration." (PMID 33329538, 2020). "Here we demonstrate that elevated levels of Δ133TP53β isoform characterize prostate cancers with immune cell infiltration, particularly T cells and CD163+ macrophages." (PMID 31431617, 2019).
prostate carcinoma (continued). "The most abundant double positive pixel class was CD68+/CD163+ and the most abundant triple positive pixel class was CD68+/CD163+/CD206+ (up to 29% of CD68-mask in a case of prostate cancer)." (PMID 30619287, 2018). "The CD163 level of the level four lymph node with metastatic focus of prostate carcinoma was 42.91%." (PMID 28716144, 2017). "CD163+ TAM, which have similar properties to M2 macrophages, are associated with an immunosuppressive microenvironment and unfavorable clinical outcomes in breast, bladder, ovarian, gastric, and prostate cancers." (PMID 34777389, 2021). "Similarly, in human prostate cancer there was an increase in expression of CD163, a monocyte and macrophage-specific scavenger receptor, in elderly patients which corresponded with poorer survival." (PMID 33441138, 2021). "Importantly, higher levels of CD163+ macrophages were detected in the prostate cancer sections (Chinese cohort) resected after preoperative ADT in comparison to the corresponding tissues collected before therapy." (PMID 33194645, 2020). "Conversely, the negative draining lymph node in the SCC patient with metastatic prostate adenocarcinoma to the cervical lymph nodes demonstrated a large CD163 population of cells, as did the interface of the metastatic focus of prostate cancer and surrounding lymph node." (PMID 28716144, 2017). "In prostate cancer, FAP+ stromal programmes co‐occur with immunosuppressive myeloid states (e.g., CD163+/SPP1+ macrophages) and FAP itself can also promote macrophage activation and tissue remodelling." (PMID 41410015, 2026). "Diverse PD-1, CD163, and FOXP3 profiles were observed in primary and metastatic microenvironments of prostate cancer." (PMID 41179298, 2025). "In this study, we performed immunohistochemical staining on prostate cancer specimens using antibodies against EAF2 and CD163, a marker of M2 macrophages." (PMID 38969982, 2024). "In prostate cancer, high expression of the circular RNA, circSMARCC1, correlated positively with colonization of CD68+/CD163+/CD206+ TAM colonization in the TME." (PMID 39199574, 2024). "We therefore performed double immunofluorescence labeling of CD163, a marker of M2 macrophages, and PLK1 in a prostate cancer tissue microarray." (PMID 33197890, 2020). "Increased infiltration of CD163+ cells correlated with higher Gleason score and incidence of metastasis, as well as lower rates of CSS in a cohort of 234 Swedish prostate cancer patients." (PMID 33194645, 2020). "PLK1 was positively correlated with CD163 in prostate cancer (Pca) samples (r=0.69, p<0.01), but not in benign prostatic hypertrophy (BPH) samples (r=0.12, p=0.63)." (PMID 33197890, 2020). "The number of CD163 and CD206 positive cells was increased in prostate cancer tissues induced by intraprostatic injection of LNCaP cells stably transfected with SFMBT2 shRNA and in prostate cancer tissues of patients." (PMID 32971847, 2020). "The negative draining lymph node demonstrated a large CD163 population of cells as did the interface of the focus of prostate cancer and surrounding lymph node." (PMID 28716144, 2017). "Contrastingly, a prostate cancer trial of neoadjuvant SBRT before radical prostatectomy conducted in only six patients revealed that immune environment was altered 2 weeks after SBRT, with a reduction in CD8+ T cells and an increase in CD68 and CD163 macrophages." (PMID 36358608, 2022).
oral squamous cell carcinoma (28 papers, 2014 to 2025). "More recent studies revealed that CAFs release chemokines to recruit MØs to the tumor, and the infiltration of CAFs are associated with the number of CD68+ or CD163+ MØs in patients with oral squamous cell carcinoma." (PMID 37254126, 2023). "Supporting these findings, a study in oral squamous cell carcinoma found the presence of CAFs to be associated with increased presence of CD163+ macrophages and worse survival." (PMID 35217711, 2022). "The positive correlation between PFKFB3 and CD163, CD31 suggested that PFKFB3 possibly promoted angiogenesis through modulating the infiltration of CD163 + tumor-associated macrophages (TAMs) in oral squamous cell carcinoma." (PMID 35784750, 2022). "In oral squamous cell carcinoma, CD163 was a prognostic biomarker and associated with poor survival." (PMID 34395626, 2021). "According to another hypothesis, PFKFB3 may facilitate angiogenesis in oral squamous cell carcinoma by regulating the infiltration of CD163+ tumor-associated macrophages (TAMs), as the expression of PFKFB3 was correlated with CD163 and CD31." (PMID 33671514, 2021). "Macrophage polarization to M2-type is characterized by CD163 expression in oral squamous cell carcinoma, and the CD163/CD68 ratio can be used as a measure for M2 polarization." (PMID 41511327, 2025). "For instance, IL-10 and TGF-β1 derived from CAFs up-regulate the expression of CD163 in monocytes in oral squamous cell carcinoma." (PMID 37254126, 2023). "Additionally, there was a positive correlation between the CMTM6 expression and the infiltration of CD163+ macrophages in oral squamous cell carcinoma (OSCC)." (PMID 37726578, 2023). "CD163-positive macrophages contribute to the aggressiveness of oral squamous cell carcinoma." (PMID 34178651, 2021). "In oral squamous cell carcinoma, PD-L1 on CD163+ CD206+ TAMs directly inhibited cytotoxic T cells." (PMID 33946835, 2021). "The number of CD163+ TAMs increased with tumor grade in oral squamous cell carcinoma." (PMID 33807310, 2021). "In addition, several researchers have reported that CD163+ macrophages promote angiogenesis in oral squamous cell carcinoma." (PMID 32075061, 2020). "CD163 and CD204 are general markers for macrophage activation in human tumors, and CD163+/CD204+ TAMs promote T-cell apoptosis and immunosuppression in oral squamous cell carcinoma." (PMID 39437149, 2025). "A systematic review and meta-analysis of immune markers in HNSCC confirmed these findings, highlighting that CD163+ and M2 macrophages, along with CD57+ NK cells, are the most influential prognosticators of survival in patients with oral cavity SCC." (PMID 39199313, 2024). "Dual CD163+CD204+ TAMs possibly play a key role in the invasion and metastasis of oral squamous cell carcinoma (OSCC) by T-cell regulation via IL-10 and PD-L1 production, more valuable than CD163+CD204− TAMs or CD163−CD204+ TAMs." (PMID 33763066, 2021). "Dual CD163+CD204+ TAMs possibly play a vital role in the invasion and metastasis of oral squamous cell carcinoma by T-cell regulation via IL-10 and PD-L1 production, relative to CD163+CD204− TAMs or CD163−CD204+ TAMs." (PMID 33763066, 2021). "We thus examined the influence of cancer cells on the differentiation of monocytes to TAM subsets, including CD163+, CD204+, and CD206+ cells, in oral squamous cell carcinoma (OSCC) using immunohistochemistry, flow cytometry, and a cytokine array." (PMID 34502382, 2021). "This study investigated the clinical relevance of TAM infiltration in oral squamous cell carcinoma (OSCC), evaluating CD68 (M1 and M2 macrophage marker) and CD163 expression (M2 macrophage marker) in the tumor nests and surrounding stroma." (PMID 32630659, 2020). "In the present study, we investigated the localization of CD163- and CD204-positive cells in oral squamous cell carcinoma (OSCC)." (PMID 28496107, 2017).
oral squamous cell carcinoma (continued). "Although preclinical studies demonstrated that TAMs preferentially express CD163 and CD204, the TAM subsets in oral squamous cell carcinoma (OSCC) remain unknown." (PMID 28496107, 2017).
cervical carcinoma (27 papers, 2014 to 2026). A carcinoma arising from either the exocervical squamous epithelium or the endocervical glandular epithelium. "Consistently, in cervical cancer and oral carcinomas, high levels of CD163+ TAMs infiltration were also associated with worse disease-free survival (DFS)." (PMID 38189834, 2024). "Further, the high density of CD163+ M2 macrophages was associated with the short survival of cervical cancer patients." (PMID 36611857, 2022). "For instance, infiltration of CD40+ macrophages in CRC and of CD14+CD163− macrophages in cervical cancer were associated with a favorable prognosis." (PMID 24723924, 2014). "Protein expressions of STAT3, NF‐κB, CD163, and CD204 in cervical cancer and the correlation of association between them." (PMID 41263059, 2025). "Cytoplasmic staining of NF-κB transcription factor and CD163 were identified in 65.8% and 65.6% of 691 patients with cervical cancer, respectively." (PMID 39061137, 2024). "The association correlation between the expression of CD204+ and CD163+ M2-TAM with STAT3/NF-κB signaling pathways in the tumor microenvironment (TME) was studied in 691 patients with cervical cancer." (PMID 39061137, 2024). "To evaluate the role of M2 macrophages in cervical cancer, we first detected the expression of CD163, which is considered an M2 macrophage marker, in 151 biopsy specimens from patients with cervical cancer who received radical radiotherapy." (PMID 36900416, 2023). "H-score was used to analyze the expression of CD20, CD57, CD68 and CD163 in cervical cancer microarray." (PMID 37642715, 2023). "In cervical carcinoma, the presence of CD163+ macrophages is related to a greater number of infiltrating CD3+CD8-FoxP3+ lymphocytes and a poor patient prognosis." (PMID 37048119, 2023). "On the other hand, the two groups used quantitative data to analyze the number of CD163+ TAM between cervical cancer and paracarcinoma or normal tissue." (PMID 33928349, 2021). "And six studies showed that the count of CD68 and CD163 TAMs in tumor stroma or nest was related to the occurrence and development of cervical cancer." (PMID 33928349, 2021). "The results of six articles showed that the high expression of CD68 and CD163 TAMs in tumor stroma or nest was correlated with the clinicopathological features of cervical cancer." (PMID 33928349, 2021). "On the one hand, three publications reported CD163+ TAM density in cervical cancer and paracarcinoma or normal tissue." (PMID 33928349, 2021). "In cervical cancer, high counts of CD68+ (M1) and CD163+ (M2) macrophages are significantly correlated to high-risk HPV infection and carcinogenesis." (PMID 34830902, 2021). "In transition from CIN to cervical cancer, the density of CD163+ macrophages increases, indicating a polarization towards a M2 subtype." (PMID 34830902, 2021). "In the included studies, the density of CD68+ and CD163+ TAM in cervical cancer was significantly enhanced than those in paracarcinoma or normal tissue." (PMID 33928349, 2021). "Collectively, the results led us to conclude that levels of ZEB1 were upregulated in the hypoxic area of human cervical cancer specimens, which in turn coincided with higher accumulation of CD163+ TAMs." (PMID 31263103, 2019). "This study showed that high ZEB1 expression in hypoxic cervical cancer cell islets was positively correlated with CD163+ TAM accumulation." (PMID 31263103, 2019). "First, we assessed whether the cellular expression of CD204+ or CD163+ M2‐TAM correlated with the STAT3/NF‐κB signaling pathways in the tumor microenvironment (TME) of 95 patients with cervical cancer." (PMID 41263059, 2025). "However, CD68+CD163+ (double positive) macrophages were numerous in the TC from cervical cancer tissues and the increased densities of both markers were associated with poor prognosis." (PMID 33995627, 2021).
cervical carcinoma (continued). "Previous reports and our results have pointed out that CD163 may have a key role in exploring the effectiveness of radiotherapy in cervical cancer radiotherapy." (PMID 34414195, 2021). "However, as can be seen from the results of this meta-analysis, CD68+ TAM and CD163+ M2 TAM density in cervical cancer were significantly enhanced than those in paracarcinoma or normal tissue." (PMID 33928349, 2021). "CD3+ tumor infiltrating T cells (TILs), CD45RO+ TILs, CD4+ TILs, CD8+ TILs, FOXP3+ TILs (regulatory T cells, Tregs), CD68+ tumor associated macrophages (TAMs), CD163+ TAMs, and PD-L1+ tumor cells were immunostained in formalin-fixed paraffin-embedded (PPFE) tissues from 96 cervical cancer patients." (PMID 31616592, 2019). "Interestingly, our results showed a strong association correlation between CD163 + CD204 + M2TAM, via STAT3/NF-κB pathways and the expression of CD25, FOXP3, MIF, and IL-17 in 56.2%, 76.3%, 85.2%, and 86.1%, respectively, of 691 patients with cervical cancer." (PMID 39061137, 2024). "Taken together, these results suggest that density patterns of different immune cell markers (namely CD3, CD4, CD8, CD20, CD57, CD68, and CD163) could be used to predict the prognosis of patients with cervical cancer and aid in evaluating the effectiveness of adjuvant chemoradiotherapy." (PMID 33995627, 2021). "Furthermore, PFS was lower in the high-CD163 expression group than in the low-CD163 expression group (p < 0.05), suggesting that M2 macrophages may play a role in the radiosensitivity of cervical cancer." (PMID 36900416, 2023). "Accordingly, a study with human cervical carcinoma lines showed that tumor-derived IL-6 and PGE2 were responsible for skewing monocyte differentiation toward a CD14+CD163+ M2-type phenotype, and that this was reversible upon co-incubation with Th1 cells." (PMID 24723924, 2014). "Our results showed that CD163 + CD204 + M2-TAM via STAT3/NF-κB signaling pathways was strongly responsible for increasing protein factors of EMT and invasion (MMP9), reverberating in a worse prognosis scenario in patients with cervical cancer." (PMID 39061137, 2024). "In cervical cancer, the presence of macrophages with the M2 phenotype (CD14+CD163+PD-L1+) may be a factor that decreases patient survival." (PMID 37048119, 2023). "Our experiments demonstrate that EVs from cervical cancer patients after radiotherapy contributed to the M2-like to M1-like phenotype transition (increased expression of CCR7, TNFα and iNOS, and decreased expression of CD163 and IL-10)." (PMID 35062905, 2022). "Moreover, in cervical cancer, when macrophages are cultured in a medium with human sera, CD206++ is the marker of M2a macrophages, CD163++ is the marker of M2c macrophages, and CD80++ is the marker of M1 and M2b macrophages." (PMID 35805111, 2022). "Our results demonstrated that radiotherapy of cervical cancer induced an increase in the number of TAMs and a change in their subtype from the M2-like to the M1-like phenotype (increased expression of CCR7 and decreased expression of CD163)." (PMID 35062905, 2022). "The results showed that the high density of CD3+ T cells, CD4+ T cells, CD8+ T cells, CD68+ M cells and CD163+ M2 cells was significantly related to the poor prognosis (p < 0.001), and CD20+ B cells and CD57+ NK decreased with the progression of cervical cancer." (PMID 36611857, 2022). "The correlation coefficient between CD68+ M cells and CD163+ M2 cells was 0.8, also an evident positive correlation; moreover, CD68+CD163+ double positive M2 macrophages were also numerous in the TC from cervical cancer tissues." (PMID 33995627, 2021). "F4/80+/CD11b+ /CD163+ cells were undetectable in healthy mice as well as in animals bearing SiHa cervical carcinoma xenograft(s), suggesting that TAMs do not play a role in our mouse model." (PMID 29774117, 2018).
cervical carcinoma (continued). "This exploratory study of cervical cancer revealed that patients with no tumor progression within 2 years after starting treatment had lower expression levels of PD-L1 and CD163 at the brachytherapy midpoint and that the expression rate of these molecules was related to the 2-year PFS." (PMID 36823665, 2023). "The densities of CD3+ T cells, CD8+ T cells, and CD163+ M2 cells were higher in squamous cell carcinoma (SCC) than in non-SCC types (P < 0.005, P < 0.037, and P < 0.025, respectively), whereas CD57+ cells were increased in non-SCC cervical cancer (P < 0.011) compared with SCC." (PMID 33995627, 2021).